OCLN (occludin)
Diseases named in the same sentence as OCLN in open-access papers (continued):
Sharing a sentence is not in itself a finding about the gene and the disease.
infection (continued). "Similarly, immunostaining of the Caco-2 cells confirmed more severe membrane mislocalization of Claudin-1, Occludin, and E-cadherin after infection with the strains carrying spvB at 3 h p.i.." (PMID 33392110, 2020). "Infection with E. coli CFT073 led to an increased expression of both occludin and claudin-14 predominantly in the upper layers of mature umbrella cells close to lumen, suggesting a local vitamin D response that further diminished towards the basal layers of lamina propria or submucosa." (PMID 31930458, 2020). "Additionally, the results of the confocal imaging were supported this view, the distribution of claudin-1 in LPS infection was observed to have the stronger discontinuous distribution and fainter staining than ZO-1 and occludin." (PMID 31949265, 2020). "In addition, C83901 infection decreased occludin mRNA expression in IPEC-J2 cells at 4 h post stimulation, while IL-17C exerted the opposite effect." (PMID 31221216, 2019). "No changes in protein content occurred at early time points, however, a trend for a decrease of ZO-1, Occludin, and Claudin-5, could be observed at 32 h of infection." (PMID 31191497, 2019). "PSaV then hijacks occludin as a coreceptor for entry and infection." (PMID 30463963, 2019). "Moreover, the infection with E. hirae induced an increasing of TJ permeability, accompanied by a decreasing of ZO-1 and occludin positive staining." (PMID 29932149, 2018). "Infection with EIEC caused a significant reduction in serine phosphorylation of occludin and tyrosine phosphorylation of ZO-1, without a substantial change in the abundance of these proteins." (PMID 30405050, 2018). "Moreover, it was reported that the intestinal tight junction proteins claudin-1, claudin-4 and occludin mRNA expression in the jejunum at 14 days post infection (dpi) were significantly decreased by a S. Typhimurium challenge in broilers." (PMID 28208612, 2017). "Moreover, the mRNA levels of occludin were significantly down-regulated at 12 h after infection with A. hydrophila, (P < 0.05) and then increased to roughly the same levels as PBS-stimulated controls at 72 h." (PMID 28484272, 2017). "While CD81 alone is not sufficient for HCV entry, a recently published mouse model expressing known human entry receptors demonstrated that CD81 had to be co-expressed with occludin, scavenger receptor type B class I, and claudin 1 for optimal infection of murine hepatocytes." (PMID 29121670, 2017). "Astrovirus has been shown to increase epithelial cell permeability upon infection of Caco-2 cells in vitro, possibly due to a reduction in actin fibers, reduction of occludin from the junctional complex, and redistribution of e-cadherin 24 h post-infection (hpi)." (PMID 28117758, 2017). "Since infection with F. tularensis showed a slower and graduated response than B. thailandensis we analysed the expression and localisation of the tight junction protein occludin in F. tularensis infected BECs by confocal fluorescence microscopy." (PMID 27527221, 2016). "In addition, the infection of CFBE41o- cells with B. contaminans decreases tight junction protein 1, ZO-1, and claudin-1, as well as occludin and indicated that tight junction degradation occurs via a decrease in numerous protein components." (PMID 26636042, 2015). "In addition to the four essential factors for HCV entry, CD81, SR-BI, claudin-1 and occludin, several additional factors facilitate infection." (PMID 25701818, 2015). "E44 infection significantly reduced occludin expression in the cortex." (PMID 21966399, 2011). "The cleavage of occludin mediated by MMP-8 in the first extracellular loop suggested that the C-terminal part of occludin is not affected during infection and therefore remains associated with the membrane and still interacts with ZO-1." (PMID 20442866, 2010). "Since MMP-8 resulted in cleavage of occludin we next analyzed whether infection of HBMEC triggers release of active MMPs." (PMID 20442866, 2010).
infection (continued). "In addition, the Occludin was transiently upregulated in the early stage of MVC infection, and whether it acts as an assisting receptor for MVC entry into cells still needs to be further investigated." (PMID 40142587, 2025). "Collectively, our study provides the first evidence that there is a direct interaction between the structural protein VP2 of MVC and ROCK1, and that the tight junction protein Occludin can serve as a potential co-receptor for MVC infection, which may offer new targets for anti-MVC strategies." (PMID 40142587, 2025). "In addition, the tight junction protein Occludin in the colon tissue of each group of mice was examined by protein immunoblotting, and the results showed that Occludin was significantly downregulated after infection." (PMID 40076603, 2025). "This infection model recapitulates breathing-like stretch and culture of epithelial cells at the air–liquid interface and resulted in clinically relevant cytopathic effects including cell rounding of alveolar type 2 cells and disruption of the tight junction protein occludin." (PMID 39697363, 2024). "Importantly, secretion of HtrA by the bacteria during infection in vivo or experiments with the recombinant proteins in vitro resulted in cleavage of the epithelial cell junction components E-cadherin, occludin, and claudin-8, which opens the tight and adherens junctions, respectively." (PMID 37183214, 2023). "Our results indicate that resistin secreted by PAMs reduces claudin-5 and occludin expression in co-cultured PAECs and increases the permeability of monolayer PAECs, implying that resistin plays an important role in maintaining endothelial integrity during pathogen infection." (PMID 36694280, 2023). "Moreover, PoSaV infection decreases the expression of OCLN to facilitate its entry and infection." (PMID 36297257, 2022). "The ALI epithelium is marked by extensive extrusion of infected ciliated cells at 24 h post infection, which stain positive for the viral RNA replication intermediate, double-stranded RNA (dsRNA), and show disorganization of tight junction proteins (i.e., ZO-1, occludin)." (PMID 34135327, 2021). "The disruption of TJ in SETC and increased permeability of the epithelial barrier induced by PCV2 could be alleviated by inhibition of JNK phosphorylation, which indicates that the JNK/MAPK pathway regulates the expression of ZO-1 and occludin during PCV2 infection." (PMID 32106883, 2020). "We therefore investigated whether RSV-infection upregulated OCLN and CLDN-4 via p63 in hTERT-HNECs." (PMID 28883651, 2017). "Our study also indicates the inner foreskin of males at risk of infection has TJ alterations such as the absence of membrane-bound claudin 4, extended membrane localization of claudin 1, and a more intense occludin staining pattern, suggestive of permeability differences." (PMID 25268493, 2014). "Similarly, rhinovirus infections have been shown to down-regulate the transepithelial resistance of nasal epithelial cells by reducing the mRNA expression of ZO-1, E-Cadherin and occludin.In addition to infection, allergen challenge can also break down TJ and AJ proteins by proteolysis." (PMID 24340021, 2013). "In addition, our data showed the involvement of MMP-8 in morphological (occludin relocation) and functional (permeability increase) alterations, and blocking MMP-8 activity preserved occludin attached at the cell membrane under infection and reduced increase of permeability." (PMID 20442866, 2010). "A key contribution of this study is the demonstration of AZM in enhancing barrier integrity by increasing the expression of key TJ proteins, specifically claudin-1 and occludin, following HRV-1b infection." (PMID 40641604, 2025). "These include murine genes incompatible with HCV biology (CD81, OCLN, TRIM26, CypA) and those murine factors that actively inhibit infection (CD302, CR1L)." (PMID 40899815, 2025).
infection (continued). "During the early stage of MVC infection, the RhoA/ROCK1/MLC2 signaling pathway is activated, resulting in TJ dissociation, Occludin exposure, and an increase in the permeability of the cell membrane, all of which facilitated MVC entry into host cells." (PMID 40142587, 2025). "In mouse mammary gland tissue infection induced by K. pneumoniae, pre-treatment with C-EVs, M-EVs or CM-EVs augmented Nrf2/GPX4 and ZO-1/Occludin expression, diminished by K. pneumoniae infection." (PMID 39953606, 2025). "As expected, the upregulation of Occludin expression correlated with the early activation of pMLC2, which was induced by MVC and peaked at 15 min post-infection." (PMID 40142587, 2025). "The IHC results showed that compared with normal mouse duodenal villi, the immune-positive signals of ZO-1, Occludin, and Claudin-1 in the duodenal mucosa were weakened to varying degrees after CPA infection." (PMID 39195835, 2024). "The results of this study revealed that PAstV−4 infection activated ERK and MLC phosphorylation, followed by the down-regulation of MUC−2, occludin, and ZO−1 proteins." (PMID 38891045, 2024). "One is that the activation of signaling pathways observed in response to infection by SARS-CoV-2 and some other viruses, e.g., MERS-CoV and Ebola, somehow influence OCLN." (PMID 37068248, 2023). "Both routes of infection require expression of the receptor complex (CD81, scavenger receptor BI, claudin-1 and occludin)." (PMID 37750869, 2023). "The infection also decreased (P < 0.05) JAM-2 and occludin expression levels compared to that of the NC and Phy 20 recovered (P <0.05) these levels as much as that of the NC group." (PMID 37334385, 2023). "Mechanistically, HAstV-induced EMT is driven by transcriptional changes; specifically, the downregulation of CDH1 and OCLN and the upregulation of the key transcriptional factor SNAI1 early after infection." (PMID 35452499, 2022). "As expected, infection with ETEC significantly (P < 0.05) reduced the relative expression of claudin-1, occludin, and zona occludens-1 mRNAs." (PMID 35736372, 2022). "We found the mRNA transcription levels of TJP1, OCLN, and CLDN5 were unaffected by the infection at 24 h, but were significantly decreased after 72 h of SARS-CoV-2 infection." (PMID 35705998, 2022). "Immunofluorescence confirmed that after infection with WT SS2, ZO-1 and occludin exhibited a discontinuous distribution in the cell membrane and occludin exhibited a granular distribution in the cytoplasm." (PMID 35921364, 2022). "The relative expression of ZO-1 and Occludin significantly decreased to 39.54% and 56.73% of the control, respectively, in HBMEC after infection for 4 h (P < 0.05)." (PMID 34163451, 2021). "Infections with C. perfringens of MDCK cells pre-treated with 0.5% Auraguard also led to a significant increase in ZO-1 expression (p < 0.0001) and occludin (p < 0.0001)." (PMID 34099034, 2021). "For intestinal barrier-related gene (Mucin-1, Mucin-2, Occludin and ZO-1), in the ileal mucosa, PRV AH02LA infection down-regulated (p < 0.05) Occludin gene expression, but had no impact on Mucin-1, Mucin-2, and ZO-1 gene expression." (PMID 31195631, 2019). "In the present study, treatment with curcumin and infection with RSV, downregulated p63 and upregulated CLDN-1 and CLDN-4, and CLDN-4 and OCLN, respectively, in HNECs." (PMID 28883651, 2017). "Nava and Vidal demonstrated in human intestinal cells that an infection with a C. perfringens type C strain induced a significant drop on TEER and this change was mediated by redistribution of TJs protein occludin and Claudin-3." (PMID 28208612, 2017). "We previously reported that OCLN and CLDN-4 were upregulated via NF-κB by infection with RSV in HNECs21." (PMID 28883651, 2017).
infection (continued). "In the HCV disease models, it was demonstrated that despite the expression of viral entry factors such as human Occludin (OCLN) and CD81 in transgenic C57BL/6 mice, in vivo infection with HCV was restricted." (PMID 29083392, 2015). "After infection with HCVpp, satisfying infection levels were obtained when cells expressed at least SRB1 in combination with OCLN/wt or OCLN/P24A." (PMID 26561856, 2015). "PAMPs of P. aeruginosa such as lipoteichoic acid and the cell wall lipoproteins sensed by TLR2 induce cleavage of tight junction proteins, occludin and ZO1, that facilitate neutrophil transmigration to the site of infection in the airway." (PMID 23527288, 2013). "The subsequent interactions between E2 and other cell surface receptors and/or co-receptors, including CD81, claudin, occludin, and SR-BI, probably stabilize HCV attachment and therefore result in specific infection of hepatocytes." (PMID 23844141, 2013). "In Western blotting, expression of G and M2-1 proteins after infection with RSV was inhibited from 1 μg/ml MG132, and upregulation of phospho-NF-κB, claudin-4 and occludin after infection with RSV was increased at 10 μg/ml MG132." (PMID 24058438, 2013). "In agreement with the previous findings showing downregulated expression of OCLN and CLDN-1 in Huh7 cells after infection with JFH-1 HCVcc, the level of OCLN and CD81 expression significantly decreased in Jurkat T cells infected with native HCV." (PMID 23626783, 2013). "Synchronized infection assays showed that glycosaminoglycans and SR-BI mediated host cell binding, while CD81, CLDN1 and OCLN all acted sequentially at a post-binding stage prior to endosomal acidification." (PMID 23555257, 2013). "Such ependymal disruption correlates with infection-induced increases in MMP8, 3, 12, 2, 9 and 16 in addition to dislocated/rearranged patterns of ependymal junction proteins including occludin, cadherin, catenin α and β." (PMID 22731103, 2012). "Cell lysates were generated at different time points after infection with N. meningitidis MC58 and analyzed for occludin expression." (PMID 20442866, 2010). "The permeability, the distribution and expression of tight junction proteins (such as Claudin-1, Occludin, JAM-1 and ZO-1) and the cytoskeleton were examined when infected with EIEC or adhesived of L. plantarum after infection." (PMID 19331693, 2009). "In contrast to claudin‐1, occludin mRNA expression was downregulated by infection, and pre‐colonization with DPM did not prevent it." (PMID 41474380, 2026). "Immunohistochemistry, western blots, and immunofluorescence data showed that infection with WT CR but not ΔescN CR significantly reduced the expression of occludin and ZO‐1, which was restored by butyrate supplementation." (PMID 39807021, 2025). "Similarly, the presence of NTHi-induced upregulation of occludin (OCLN) and MYH9 possibly improves cellular polarity as a resistance mechanism to NTHi infection." (PMID 40492732, 2025). "While AZM decreased claudin-1 gene expression in non-infected cells, it increased claudin-1 and occludin expression following HRV-1b infection." (PMID 40641604, 2025). "We observed that mAIEC infection of Ptpn2∆IEC mice decreased levels of the transmembrane tight junction protein, occludin, and the adherens junction protein, E-cadherin compared to Ptpn2∆IEC + PBS controls, however the effect of mAIEC was not significantly different between mouse genotypes." (PMID 40955058, 2025). "Furthermore, it was found that hBD-2 significantly increased the mRNA expression of occludin and ZO-1 in HNECs after USA500 infection (p < 0.05 and p < 0.01, respectively)." (PMID 40415954, 2025). "Here, we observed that neither ZO-1 nor occludin distribution was altered during infection, furthermore corroborating that tight junctions remain intact during N. meningitidis infection." (PMID 38756230, 2024).
infection (continued). "Infection of the H9N2 AIV was indicated by virus NS1 protein, and the amount of five cell surface proteins relating to bacteria adhesion, including fibronectin, integrin α5, occludin, cortactin, and ZO-1, was measured by Western blot." (PMID 38415626, 2024). "Compared to RV-A1-infected placebo-treated cells, RV-A1-infected ECSN6-treated cells showed no increase in occludin at 24 h post-infection, probably because RV-A1 did not disrupt intercellular junctions in ECSN6-treated cultures." (PMID 39538325, 2024). "Taken together, these results demonstrate that OCLN can interact with SARS-CoV-2-S1 directly and has an interaction with ACE2, suggesting that a complex formed among three molecules mediates virus entry and infection." (PMID 37068248, 2023). "Both rVSV-eGFP-S and SARS-CoV-2-mNG infections were able to alter OCLN expression and distribution but provided no observable changes on ZO-1 and Claudin-1." (PMID 37068248, 2023). "Taken together, these data demonstrate that OCLN overexpression significantly enhances infection and replication of SARS-CoV-2 in permissive cells, again emphasizing that OCLN plays an important role in virus-induced cell-to-cell fusion and virus cell-to-cell transmission." (PMID 37068248, 2023). "Interestingly, expression of TJP1, F11R, OCLN and CLDN5 were transiently increased after 2 or 4 days of infection before their downregulation (median increase up to 28.4% for TJP1, 33.5% for F11R, 110.4% for OCLN and 51.6% for CLDN5)." (PMID 37537664, 2023). "Based on GFP signals, OCLN knockdown resulted in significant inhibition of the ability of rVSV-eGFP-S virus to infect and replicate in Vero-E6 cells and A549-hACE2 cells relative to controls with a normal OCLN content, which is consistent with the findings observed with SARS-CoV-2-mNG infection." (PMID 37068248, 2023). "Eta variant at MOI 1 also transiently induced an increase in tight and adherens junction expression at 2 dpi (median increase for TJP1: 33.5%; F11R: 38.3%; OCLN: 25.9%; CLDN5: 96.6% and CDH5: 74.5%) before expression levels returned to the uninfected condition ones after 6 days of infection." (PMID 37537664, 2023). "Collectively, these observations suggest that Atl contributes to the redistribution of ZO-1 and occludin without affecting TJ protein expression during SS2 infection." (PMID 35921364, 2022). "However, ZIKV-PR and ZIKV-U significantly downregulate the expression of ZO-1, OCLN, and CLDN-5 and penetrated the brain parenchyma early after infection." (PMID 36297257, 2022). "The expression of ZO-1, OCLN, and CLDN-1 was also determined in nasal microvessels to validate whether PEDV infection disrupts the integrity of nasal microvessels." (PMID 35435723, 2022). "The expression of Occludin in HBMECs treated with siRNA decreased significantly compared with that in HBMECs not treated with siRNA after infection (p < 0.01)." (PMID 36289622, 2022). "In the absence of maltol, challenge infection (NC group) with E. maxima decreased (P = 0.033) the gene expression of occludin (1.4 × 10−2-8.8 × 10−3) in the distal jejunum compared to that in the CON group." (PMID 34095279, 2021). "The group supplemented with 1% thymol nanoemulsion showed the most significant (p < 0.05) upregulation of occludin with 2.93 and 2.70-fold pre- and post-infection and JAM with 2.77 and 2.26-fold pre- and post-infection c,d, respectively when compared with control groups." (PMID 33833292, 2021). "The expression of Occludin 6 h post-infection was not significantly different among any of the groups (P > 0.05)." (PMID 32180765, 2020). "In contrast to the direct infection pathway, our results proposed a paracellular pathway for the ZIKV crossing the placental barrier by disrupting the cellular tight junction of the barrier cells through degradation of ZO-1 and occludin." (PMID 32153526, 2020).